STAT3 (signal transducer and activator of transcription 3)
Diseases named in the same sentence as STAT3 in open-access papers (continued):
Sharing a sentence is not in itself a finding about the gene and the disease.
non-Hodgkin lymphoma (14 papers, 2013 to 2025). Distinct from Hodgkin lymphoma both morphologically and biologically, non-Hodgkin lymphoma (NHL) is characterized by the absence of Reed-Sternberg cells, can occur at any age, and usually presents as a localized or generalized lymphadenopathy associated with fever and weight loss. "Non-Hodgkin’s lymphoma and solid tumors share two targets: signal transducer and activator of transcription 3 (STAT3) and BCL2 apoptosis regulator (BCL2)." (PMID 41041638, 2025). "In non-Hodgkin lymphoma, STAT3 binds to the PD-L1 gene promoter, which upregulates PD-L1 expression in vitro and in vivo." (PMID 35971127, 2022). "In non-Hodgkin lymphoma, STAT3 binds to the PD-L1 gene promoter, resulting in upregulation of PD-L1 expression in vitro and in vivo." (PMID 31835799, 2019). "A recent study on signaling profiles in non-Hodgkin lymphomas suggested that basal STAT3 (pY705) levels were elevated in CLL cells relative to normal B cells, but the statistical significance was not indicated." (PMID 29507689, 2018). "Besides NSCLC, STAT3 activation is often observed in non-Hodgkin lymphomas, including follicular lymphomas (FL)." (PMID 39985075, 2025). "Among the 10 non-Hodgkin's lymphoma patients, none (0%) had high expression of STAT3, 1 patient (10%) had low expression of STAT3, and 9 patients (90%) showed no expression of STAT3." (PMID 38817669, 2024).
Salmonella Infections (14 papers, 2013 to 2025). Infections with bacteria of the genus SALMONELLA. "The addition of clove extract and eugenol effectively inhibited the excessive activation of the JAK2/STAT3 signaling pathway induced by Salmonella infection (P < 0.05)." (PMID 40059168, 2025). "The relationship among lactate and SPI-2 expression, SteE translocation, and phosphorylation of STAT3 during Salmonella infection of macrophages was further investigated." (PMID 37796020, 2023). "It was reported both in vivo and in vitro that STAT3 is activated early after WT Salmonella infection." (PMID 36262184, 2022). "In agreement with our data, this phosphorylation in STAT3 was shown to polarize macrophages towards an M2 phenotype in models of salmonella infection, myocardial infraction and cancer." (PMID 34208043, 2021). "Epithelial STAT3 activation seems to promote Salmonella infection (bottom), which suggests that enforced production of the STAT3 inducer IL-6 serves Salmonella to propel the establishment of its infection niche." (PMID 32071273, 2020). "On the other hand, FOXO signaling (TNFSF10, PRKAB1, GADD45B, STK4, STAT3), Salmonella infection (ARPC2, ARPC5L, CCL3L3, CCL4) and lysosome (LAPTM4B, HGSNAT, CD164, ATP6V0A2) pathways were up-regulated, albeit weakly, in the HLA-DR- Teff subset." (PMID 30231065, 2018). "Expression of PipA, GtgA or GogA did not alter the levels of other transcription factors activated by Salmonella infection such as c-Jun or STAT3." (PMID 26933955, 2016). "Salmonella infection led to the overactivation of the JAK2/STAT3 signaling pathway." (PMID 40059168, 2025). "We therefore tested whether the STAT3 activation we observed in epithelial cells in response to Salmonella infection was the result of an autocrine and/or paracrine signaling pathway." (PMID 24098123, 2013). "We found no detectable STAT3 phosphorylation in cells treated with any of the infected cell supernatants indicating that STAT3 activation as a consequence of Salmonella infection is not likely to be the result of autocrine or paracrine pathways." (PMID 24098123, 2013). "Effector activation of STAT3 may at first seem counterintuitive, as the host is already producing IL-6 in response to Salmonella infection, and we previously observed activation of STAT3 in infected mice even in the absence of SarA." (PMID 40188438, 2025).
benign prostatic hyperplasia (13 papers, 2005 to 2025). A non-cancerous nodular enlargement of the prostate gland. "We observed a strong nuclear immunoreactivity for STAT3 and STAT5A in 93% (n=14/15) and 80% (n=12/15) of CRPC cases, respectively, compared with benign prostatic hyperplasia (BPH)." (PMID 29156772, 2017). "To this end we are studying the oncogenic role of STAT3 activation in rat prostate epithelial cell lines NRP-152 and human benign prostatic hyperplasia line BPH-1." (PMID 15647107, 2005). "Therefore, this study conducted a pharmacodynamic evaluation of rape pollen maca chewable tablets on benign prostatic hyperplasia, investigated their impact on gut microbiota, and further explored the IL-6/JAK2/STAT3 signaling pathway in prostatic tissues." (PMID 41472815, 2025).
brain injury (13 papers, 2013 to 2025). Acute and chronic (see also brain INJURIES, CHRONIC) injuries to the brain, including the cerebral hemispheres, CEREBELLUM, and brain STEM. "Specifically, AR is necessary for myelin regeneration and astrocyte function within the CNS, processes that require STAT3 signaling and are dysregulated after traumatic brain injury." (PMID 40117367, 2025). "For instance, it has been reported that JAK2 and STAT3 inhibitors can block an increase in pro‐inflammatory protein levels following ischemic brain injury." (PMID 36627822, 2023). "Likewise, traumatic brain injury-induced IL-23 upregulation enhanced neuronal ferroptosis through STAT3 activation, while IL-23 neutralization attenuated ferroptosis, restored GPX4 and ACSL4 expression, and normalized STAT3 overactivation." (PMID 41304754, 2025). "On the other hand, ICV injection of S1P into mice reduces food intake via JAK2/STAT3 dependent signaling, signaling molecules being also involved in leptin action and may act neuroprotective in brain injury." (PMID 33946318, 2021). "STAT3 is a momentous signaling pathway, which is observed to activate in traumatic brain injury, and moreover may partake in the mediation of the restoration of neurological function (Oliva, Kang, Sanchez‐Molano, Furones, & Atkins, 2012; Zhao, Zhang, Li, Su, & Hang, 2011)." (PMID 32304289, 2020). "In this study, we revealed that controlled reoxygenation treatment could reduce neuron and glial cell apoptosis caused by hypoxia and exert an anti-inflammation effect on hypoxia-induced brain injury mice by downregulating JAK2/STAT3 and AMPK/mTOR signaling pathway." (PMID 31719034, 2019). "Thus, blockade of STAT3 signaling in astrocytes might be beneficial to prevent excitotoxic neuronal death in models pertinent to many brain injuries with an inflammatory profile." (PMID 27287400, 2016). "Of note, in a mouse model of traumatic brain injury (TBI), we previously showed that total STAT3 expression can increase following brain insult." (PMID 39643584, 2025). "Turovsky and co-workers reported that selenium nanoparticles are able to protect cortical astrocytes and neurons against ischemic brain injuries inhibiting apoptosis inactivating caspase 3 and recruiting nuclear factors Nrf2 and SOCS3/STAT3." (PMID 35216387, 2022). "In conclusion, ASIV inhibits post-ischemic brain infiltration and activation of NK cells through STAT3 suppression, and this inhibitory effect of ASIV on NK cells plays a key role in its protection against acute ischemic brain injury." (PMID 35185544, 2021).
Burkitt lymphoma (13 papers, 2015 to 2024). A rare form of malignant mature B-cell non-Hodgkin lymphoma. "Consistent with our results here, prior work demonstrated that EBV-positive Burkitt lymphoma cells lack the canonically active Y705 p-STAT3." (PMID 38620028, 2024). "Increased ubiquitylation was also observed on several sites on the transcription factor STAT3, which plays an important role in B-cell development, as well as on GNAI2, which is also required for B-cell development, and mutated in Burkitt lymphoma and DLBCL." (PMID 26038114, 2015). "Constitutive activation of JAK2/STAT3 is a major oncogenic signaling event involved in the development of Burkitt lymphoma (BL)." (PMID 34588425, 2021). "In addition, STAT3 on Tyr705 correlates with Burkitt lymphoma (BL) chemoresistance." (PMID 32872659, 2020). "Indeed, BP-1-102, a salicylic acid-based inhibitor, was tested in preclinical models of ALL and Burkitts lymphoma with STAT3 activation, demonstrating that BP-1-102 inhibits STAT3 phosphorylation at tyrosine 705, preventing STAT3 dimerization, DNA binding, and the activation of downstream genes." (PMID 32503270, 2020). "It was reported that rituximab is able to inhibit STAT3 activity and IL-10 secretion by a CD20 positive Burkitt's lymphoma cell line, 2F7." (PMID 26315113, 2015). "Similarly, STAT3 and CEBPB in SNB19 cell line, CHAF1A in IMR32 cell line, and BCL6 in Burkitt lymphoma cell line were identified by RegEnrich, with the GSEA method, as one of the top 20 key regulators in each corresponding dataset." (PMID 35017649, 2022). "Consistent with the possibility that cholesterol was handled differently by CLL cells than other blood cancers, growth and phospho-STAT3 levels in Daudi cells, a Burkitt's lymphoma model, were not increased when LDLs were added to serum-free media." (PMID 27932296, 2017). "In brief, we showed for the first time that TG101209, a specific JAK2 inhibitor, could inhibit Burkitt lymphoma growth, induce cycle arrest, differentiation and apoptosis of BL cells, and prolong the survival of Ramos cell-bearing mice by inhibiting the JAK2/STAT3/c-MYB signaling axis." (PMID 34588425, 2021).
chordoma (13 papers, 2012 to 2025). Chordomas are rare malignant tumors arising from embryonic remnants of the notochord in axial skeleton. "STAT3-based signaling has been implicated in several chordoma studies, yet does not seem to be universally activated in chordoma." (PMID 31221659, 2019). "The plausibility of this mechanism underlying our findings is supported by data implicating STAT3 up-regulation in chordoma." (PMID 25823817, 2015). "CMTM3 suppressed the migration and invasion of chordoma cells through the EGFR/STAT3/EMT signaling pathway." (PMID 34560882, 2021). "Our data revealed that the sacral chordoma cell lines showed a significant reduction in phosphorylation of Akt, Erk, and Stat3 after treatment with cMET inhibitors." (PMID 34127734, 2021). "At present, the research on the molecular mechanism of chordoma mainly includes receptor tyrosine kinase and its downstream signaling pathways, Src/Stat3 signaling pathway and PI3K/AKT/mTOR pathway." (PMID 34888345, 2021). "Yanget al. reported growth inhibition in different chordoma cell lines after application ofSD-1029, an inhibitor of Stat3 activation." (PMID 28105324, 2016). "In addition, targeting STAT3 with experimental compounds has been shown to reduce the viability of chordoma cell lines." (PMID 40901948, 2025). "The levels of p-STAT3 expression correlated with the survival rate and severity of chordoma." (PMID 22662257, 2012). "Crizotinib inhibited chordoma cell growth, induced apoptosis and cell cycle arrest, and suppressed downstream pathways such as AKT, ERK, and STAT3." (PMID 41442054, 2025). "Taken together, CMTM3 suppresses chordomas metastasis via accelerating EGFR degradation and suppressing the EGFR/STAT3/EMT signaling pathway." (PMID 34560882, 2021). "Therefore, we tested the levels of total and phosphorylated p-EGFR (Tyr1068), p-STAT3 (Tyr705), p-AKT (Ser473) and p-ERK1/2 (Thr202/Tyr204) in chordoma cells by western blot." (PMID 34560882, 2021). "p-EGFR, p-STAT3, p-AKT and p-ERK1/2 in tumor samples from the chordoma mice model." (PMID 34560882, 2021). "Of note, our results with negative hyperplasia outcome do not rule out a chordoma-promoting potential for Brachyury, STAT3 or any other tested factor." (PMID 31221659, 2019).
chordoma (continued). "In line with the observations in cell lines, MSigDB enrichment scores revealed that interferon alpha and gamma response, inflammatory response, and IL6/JAK/STAT3 and IL2/STAT5 signaling were among the most enriched signaling axes in chordoma but not in the pan-cancer cohort." (PMID 40901948, 2025).
cutaneous melanoma (13 papers, 2012 to 2024). A primary melanoma arising from atypical melanocytes in the skin. "JAK1, JAK2 and STAT3 genotypes and alleles in 248 cutaneous melanoma patients and 274 controls." (PMID 35982955, 2022). "The K−M survival analysis revealed that the OS of patients with LGG, tenosynovial giant cell tumors (TGCT), and skin cutaneous melanoma (SKCM) in the STAT3 high expression group was significantly different (P < 0.05)." (PMID 37724127, 2023). "JAK1, JAK2, and STAT3 significant combined genotypes in 248 cutaneous melanoma patients and 274 controls." (PMID 35982955, 2022). "STAT3 siRNA delivery via dissolving MNs is a promising approach for skin melanoma treatment with targeting inhibition efficacy and minimal adverse effects." (PMID 29348670, 2018). "JAK1, JAK2, and STAT3 haplotypes in 248 cutaneous melanoma patients and 274 controls." (PMID 35982955, 2022). "In humans, analyses of the TCGA dataset revealed positive mRNA correlations from cutaneous melanoma biopsies for expression of NLRP3 and IL‐6 (p=4.86e-20), IL‐6 and the STAT3 target gene Socs3 (p=1.82e-62), IL-1β and Socs3 (p=1.71e-31)." (PMID 34531850, 2021). "The transcript expression of STAT1, STAT3, and IRF1, three key transcription factors of the IFNγ signaling cascade, were also lower in the TCGA UVM dataset compared to the TCGA cutaneous melanomas." (PMID 29977240, 2018). "However, in the vast majority of cases, patients with skin cutaneous melanoma (SKCM; P = 0.034, HR = 0.75) with high levels of STAT3 expression had a significantly better median survival time than those with low expression." (PMID 36977736, 2023).
diabetic retinopathy (13 papers, 2011 to 2025). "The inhibition of Stat3 and STAT3 signaling can reduce apoptosis of retinal endothelial cells and delays the vision loss observed in a rat model of diabetic retinopathy." (PMID 33981252, 2021). "For instance, circ_0005015 elevates the expression of MMP-2, XIAP, and STAT3 thereby promoting the development of diabetes retinopathy via acting as a molecular sponge of miR-519d-3p." (PMID 32600379, 2020). "High glucose induces ER stress and inflammation through the activation of Stat3 in diabetic retinopathy." (PMID 31461977, 2019). "CircZNF532 could also regulate pyroptosis in RPE cells from diabetic retinopathy patients by targeting the miR-20b-5p/STAT3 axis." (PMID 35957838, 2022). "It was recently observed that CXCL9 could activate Jak2/ STAT3 signalling in podocytes and correlates with retina inflammation in patients with diabetic retinopathy." (PMID 31913856, 2020). "As such, modulation of Stat3 expression likely impacts a variety of pathways and processes in the retina and may prove to be a useful target in drug development efforts for diabetic retinopathy." (PMID 21249158, 2011).
enteropathy (13 papers, 2019 to 2025). "This is supported by overlapping symptoms of patients with STAT3 GOF and STAT5B LOF mutations, like cytopenia, short stature, and enteropathy." (PMID 37140667, 2023). "STAT1 and STAT3: enteropathy, severe viral and bacterial infections, and endocrinopathy." (PMID 34122435, 2021). "Autosomal dominant germline gain-of-function (GOF) variants in STAT3 result in a PIRD characterized by immune dysregulation and a broad spectrum of clinical features, including cytopenias, lymphadenopathy, interstitial lung disease, enteropathy, and polyendocrinopathy." (PMID 36136607, 2022). "STAT3 GOF mutation results in impairment of the regulatory T cell compartment, and patients characteristically suffer from lymphoproliferation, recurrent infections, and multisystem autoimmune disease, including type 1 diabetes, enteropathy and autoimmune cytopenia." (PMID 34248986, 2021).